CD83 (CD83 molecule)
Diseases named in the same sentence as CD83 in open-access papers (continued):
Sharing a sentence is not in itself a finding about the gene and the disease.
glioma (6 papers, 2017 to 2025). A benign or malignant brain and spinal cord tumor that arises from glial cells (astrocytes, oligodendrocytes, ependymal cells). "Here, we show that overexpression of CD83 in an immunocompetent glioma model extends survival and is associated with activation and expansion of CD8+ T cells while enhancing activating T-cell cytokine production." (PMID 39601621, 2024). "We conducted single-cell RNA sequencing of glioma samples, which revealed a select subset of human and mouse glioma cells that express CD83, a marker associated with mature antigen-presenting cells." (PMID 39601621, 2024). "These transcriptomes captured the uniqueness of CD83 tumor cells showing a combination of primitive glioma-like cell subtypes such as oligodendrocyte progenitor cell and neural progenitor cell as well as antigen-presenting cells like embryonic microglia." (PMID 39601621, 2024). "To investigate the impact of tumor cell CD83 expression on glioma outcomes, we used an immunocompetent mouse model of glioma, bioinformatic analyses of human samples, and in vitro assays." (PMID 39601621, 2024). "Collectively, these analyses identified ALTs as a rare population of tumor cells in both human and mouse glioma that possess high expression of CD83, a key mediator of the antigen presentation process." (PMID 39601621, 2024). "We also saw increased TNFα, complement, and antigen presentation signaling occurring in high CD83-scored glioma compared with low." (PMID 39601621, 2024). "Having identified ALTs in human and mouse glioma, we sought to define how CD83 expression affects in vivo tumor progression." (PMID 39601621, 2024). "To discern if modulation of CD83 expression in ALTs alters T-cell phenotypes in glioma, we examined CD8+ T-cell phenotypes in our pB-IUE mice." (PMID 39601621, 2024). "CD83 overexpression in human and mouse glioma increases survival." (PMID 39601621, 2024). "Interestingly, in addition to its effects reducing MDSC accumulation, SFN promotes the development of pro-inflammatory dendritic cells from monocytes cultured in both fresh media and glioma-conditioned media, though these are only mature DC’s (CD83+) in the presence of GCM." (PMID 28666020, 2017). "Our results show that CD83 expression in glioma leads to expression profiles related to CTL-mediated antitumor responses and highlight novel mechanisms by which tumor cells could partake in priming of T cell–mediated immunity in glioma." (PMID 39601621, 2024). "Given that CD83 functions as a regulator of MHC expression and T-cell development, our data introduce that it as a possible enhancer of self-antigen presentation in glioma cells, suggesting that ALTs could be promoting antitumor CTL responses by direct tumor–CTL priming of CD8+ T cells." (PMID 39601621, 2024).
asthma (5 papers, 2014 to 2025). "The present study explores for the first time the role of CD83 expression by lung‐resident Tregs in the steady state and during asthma to understand its importance in barrier tissues." (PMID 39955650, 2025). "Overall, our results highlight CD83 as a key player in tissue homeostasis and inflammatory responses, suggesting potential therapeutic implications for inflammatory disorders such as asthma." (PMID 39955650, 2025). "In immunohistochemical studies, Tsoumakidou and colleagues showed that smokers with COPD or asthma have decreased numbers of CD83 positive cells in the airways." (PMID 24742278, 2014). "It is noteworthy that exposure with crude O. felineus extract leads to the downregulation of costimulatory molecules CD83 and CD86 in LPS-induced DCs, generated from monocytes of asthma patients." (PMID 31750318, 2019).
atherosclerosis (5 papers, 2015 to 2025). A disease characterized by the build-up of fatty material and calcium deposition in the arterial wall resulting in partial or complete occlusion of the arterial lumen. "Considering the downregulation of MZp membrane-bound CD83, we sought to measure sCD83 blood levels to assess its association with subclinical atherosclerosis." (PMID 36679926, 2022). "The immune-associated genes in both atherosclerosis and osteoporosis from WGCNA mainly included TREM1, CYBB, CCR1, CD83, CD52, IL7R, and THBS1." (PMID 35937806, 2022). "It is possible that downregulated expression of CD80, CD83, and CD88 by Dx can affect pathogenesis of atherosclerosis." (PMID 27340507, 2016). "Immunostaining with these markers showed a significantly higher cells number of immature as well as mature mDCs in femoralis plaques compared to arteries without signs of atherosclerosis: 16 versus 8 CD209+ mDCs/0.1 mm2 (P = 0.012) and 19 versus 5 CD83+ mDCs/0.1 mm2 (P = 0.034)." (PMID 25960616, 2015).
HCMV infection (5 papers, 2007 to 2025). "Human cytomegalovirus infection of mature DCs was shown to cause a decrease in surface expression of CD83 which coincided with detection of a soluble form of this molecule in the cell culture medium." (PMID 26575844, 2015). "In order to analyze whether the loss of CD83 from the cell surface of mDCs after HCMV infection is a CD83 specific effect or due to a general down-regulation of mDC surface proteins, mDCs were either HCMV-infected or were left uninfected." (PMID 28203230, 2017). "Therefore, the aim of this study was to further investigate the mechanisms underlying the down-modulation of CD83 after HCMV infection of mDCs." (PMID 28203230, 2017). "Overall, the histochemical staining patterns observed in TC, SFG, and vagus nerve of CD83(+) subjects are consistent with active HCMV infection." (PMID 39698934, 2025). "In the present study, we report that upon HCMV infection of mDCs CD83 surface expression is reduced with fast kinetics, becoming significant already 12 h after infection and reaching its maximum 16 hpi." (PMID 28203230, 2017). "The results of the present study demonstrate for the first time that IE2 induces the down-modulation of CD83 very early after HCMV infection of mDCs." (PMID 28203230, 2017). "To further elucidate the mechanism leading to CD83 reduction after HCMV infection of mDCs, we aimed to identify the effector protein/s inducing CD83 down-modulation." (PMID 28203230, 2017). "Using flow cytometric analyses, we observed significant down-modulation of CD83 surface expression becoming significant already 12 h after HCMV infection." (PMID 28203230, 2017). "This group postulated that HCMV infection of mDCs mediates shedding of the immunosuppressive soluble CD83 molecule into the supernatant which subsequently leads to a reduction of DC-mediated antiviral T cell stimulation." (PMID 28203230, 2017). "In contrast, in the present study we show that HCMV infection of mDCs leads to the degradation of CD83 in a proteasome dependent manner." (PMID 28203230, 2017). "Human cytomegalovirus (HCMV) infection induced the shedding of naturally expressed CD83 by infected human DC and this soluble CD83 again suppressed allogenic T cell proliferation." (PMID 17710154, 2007). "Our observations that HCMV infection of C20 microglia is sufficient to induce CD83 is consistent (but not dispositive) with HCMV being a direct cause of the CD83(+) microglia we originally observed in‐situ within the SFG snRNA‐seq." (PMID 39698934, 2025). "Furthermore, inhibition of the proteasome almost completely restored CD83 surface expression during HCMV infection." (PMID 28203230, 2017). "Interestingly, earlier studies demonstrated that the functionally important mDC surface molecule CD83 is down-regulated upon HCMV infection resulting in a reduced T cell stimulatory capacity of the infected cells." (PMID 28203230, 2017). "HCMV histochemistry is consistent with an active HCMV infection, which may indicate an opportunity for the administration of antiviral therapy in subjects with AD and biomarker evidence of HCMV, IgG4, or CD83(+) microglia." (PMID 39698934, 2025). "Taken together these data clearly demonstrate that HCMV infection of mDCs does not lead to a shedding of a soluble form of CD83 from the cell surface but to proteasomal degradation of CD83." (PMID 28203230, 2017). "Here, we clearly demonstrated that CD83 is not lost from the cell surface of mDCs upon HCMV infection but that it is rapidly degraded via a proteasome-dependent mechanism." (PMID 28203230, 2017). "While CD83 surface expression was significantly reduced (p < 0.001), CD80 and HLA-DR were not influenced by HCMV infection." (PMID 28203230, 2017).
inflammatory bowel disease (5 papers, 2017 to 2024). A spectrum of small and large bowel inflammatory diseases of unknown etiology. "The aim of this study is to assess the impact of applied therapy, level of inflammation in biopsy specimens and phenotype of inflammatory bowel diseases on the presence of mucosal mature CD83+ dendritic cell in colonic biopsy samples." (PMID 38610835, 2024). "We found a significant difference in the presence of CD83+ DCs among different types of inflammatory bowel diseases." (PMID 32572123, 2020). "Our study also analysed the number of mature CD83+ DCs between different types of inflammatory bowel diseases." (PMID 32572123, 2020). "The DC surface receptor costimulatory molecules CD86, CD80, CD83, and CD40 generate important signals for stimulating naive T cell differentiation and may inhibit oral tolerance in not only IDDM but also inflammatory bowel disease (IBD) and multiple sclerosis." (PMID 28396662, 2017).
lung carcinoma (5 papers, 2010 to 2020). "The transfer of DC-based HHP lung cancer vaccine into serum containing conditions led to an increased expression of CD80 and CD83 within next 24 h compared to DC-based HHP lung cancer vaccine left in serum-free medium." (PMID 28187172, 2017). "Interestingly, CD83 is also expressed by tumor cells from lung cancer, cervical cancer, and Hodgkin lymphoma, and soluble CD83 has been found to be secreted by those tumor cells." (PMID 32823589, 2020). "Although cancer itself is known to be associated with reduced numbers of mature dendritic cells, this is not likely to have been a source of bias, since our study showed greater CD83 staining in COPD tissue (virtually all of which had coexistent lung carcinoma) compared to controls." (PMID 20420706, 2010). "DC-based HHP lung cancer vaccine exhibited higher expression of CD80 and CD83 when stimulated with CD40L-expressing A549 in comparison to DC-based HHP lung cancer vaccine incubated with non-transfected A549." (PMID 28187172, 2017). "DC-based HHP lung cancer vaccine [HHP+poly(I:C)] displays significantly higher expression of CD80, CD83, HLA-DR and CD86 than control immature DC [iDC], DC pulsed with HHP-killed cells alone [HHP] or DC stimulated only with poly(I:C) [poly(I:C)]." (PMID 28187172, 2017). "DC-based HHP lung cancer vaccine was not functionally exhausted by the first maturation stimuli with poly(I:C) as DC enhanced the expression of maturation associated molecules CD80 and CD83 and IL-12p70 production in response to LPS and CD40L." (PMID 28187172, 2017).
lupus (5 papers, 2017 to 2025). "In systemic lupus erythematosus (SLE), lysosomal‐associated membrane protein 3, the CD83 molecule (CD83) and programmed cell death 1 ligand 2 may be downstream targets of METTL1 and are involved in abnormal immunological responses." (PMID 39979979, 2025). "Many genes contained in the Hallmark IFN-α response and Hallmark TNF-α signaling pathways, including IFI27, IFI44, RELB, KLF6, and CD83, had significantly higher expression in lupus: We verified transcriptional changes in the naive compartment by quantitative PCR (qPCR)." (PMID 39688922, 2024). "In addition, we found the UC-MSCs induced CD1c+DCs in the lupus patients exerted tolerogenic properties by decreasing expression of CD80, CD83, CD86 and HLA-DR, decreasing production of TNFα and keeping production of IL-10." (PMID 31175312, 2019).
ovarian carcinoma (5 papers, 2017 to 2024). A malignant neoplasm originating from the surface ovarian epithelium. "Our results further show the mechanisms underlying the stimulation of proliferation and stemness of ovarian cancer cells by CD83, involving interaction with MAP3K7 and activation of MAPK signaling pathway, as well as downstream FOXO1/p21/CDK2/Cyclin B1 and STAT3/DKK1 cascades." (PMID 32823589, 2020). "Taken together, CD83 was associated with poor survival of ovarian cancer patients, and CD83 might determine the fate of ovarian cancer cells." (PMID 32823589, 2020). "Besides CD83, a large number of the CD83 highly-associated genes (Person correlation >0.5, p < 0.01) within ovarian cancer transcriptome showed higher expression in ovarian cancer cells, especially in the EpCAM+/CD45+ subtypes." (PMID 32823589, 2020). "In this study, we suggest that membrane protein CD83 activates MAPK signaling pathway through the interaction with TAK1-TAB1 complex in ovarian cancer cells." (PMID 32823589, 2020). "The intersection of the transcriptome (fold change ≥2) and proteome (fold change ≥1.5) included 83 differentially-expressed (DE) targets between CD83-KD and NC ovarian cancer cells, whereas OV-vs.-NC showed only two DE targets (CD83 and RSPH4A)." (PMID 32823589, 2020). "We first examined the roles of CD83 on the main characteristics of ovarian cancer cells, including their proliferation, stemness, apoptosis, migration, and invasion abilities." (PMID 32823589, 2020). "A great difference between CD83-KD ovarian cancer cells and the other two groups was obviously observed." (PMID 32823589, 2020). "Considering the expression of transmembrane CD83 in various tumor cells exhibiting potential therapeutic implications, this study was conducted with an aim to investigate the role of membrane protein CD83 in ovarian cancer cells." (PMID 32823589, 2020). "Although CD83 is widely described as a solid marker for mature dendritic cells, emerging pieces of evidence indicate the expression of membrane protein CD83 by various tumor cells, including ovarian cancer cells." (PMID 32823589, 2020). "On the other hand, CD83 stabilizes the expression of TAB1 in ovarian cancer cells upon protein degradation." (PMID 32823589, 2020). "Accordingly, there is positive regulation of above cell cycle/stemness factors and negative regulation of MMPs by CD83, partially explaining why CD83 advances the growth proliferation and spheroid formation but limits invasion of ovarian cancer cells." (PMID 32823589, 2020). "Using an integrated analysis of proteomic and transcriptomic data, we have observed the positive regulation of proliferation/stemness factors (e.g., cyclins-CDKs and KIT) and negative regulation of MMPs (e.g., MMP1 and MMP7) by CD83 in ovarian cancer cells." (PMID 32823589, 2020). "Emerging pieces of evidence indicate the expression of transmembrane CD83 and secretion of soluble CD83 by various tumor cells, including ovarian cancer cells." (PMID 32823589, 2020). "Consistent with this transcriptomic observation, proteomics identified that KIT was attenuated, whereas MMP1 and MMP7 were elevated in CD83-KD ovarian cancer cells." (PMID 32823589, 2020). "The increased STAT3 expression and attenuated wingless-type MMTV integration site family (WNT) antagonist DKK1 were observed in CD83-overexpressed ovarian cancer cells." (PMID 32823589, 2020). "To dissect the molecular mechanisms of CD83 in the fate determination of ovarian cancer cells, we used the immunoprecipitation, followed by mass spectrometry (IP-MS) approach, to identify protein candidates that functionally associate with transmembrane CD83." (PMID 32823589, 2020). "We have shown that CD83 advances the growth proliferation and colony formation ability but limits the migration and invasion potentials of ovarian cancer cells." (PMID 32823589, 2020).
ovarian carcinoma (continued). "Taken together, our findings demonstrated that the CD83 intracellular domain was important for its association with TAK1/TAB1 and activation of the MAPK signaling pathway, as well as CD83 function in ovarian cancer cells." (PMID 32823589, 2020). "We cannot exclude the possibility that the effects of CD83 on the fate determination of ovarian cancer cells identified in this study are partially contributed by sCD83." (PMID 32823589, 2020). "CD83 highly-associated genes, such as ITGAM, IL1B, CYBB, PIK3R5, BTK, and OSM, ectopically express in ovarian cancer cells or tissues, involving in ovarian cancer progression, hypoxia networks, and the development of chemoresistance." (PMID 32823589, 2020). "In summary, the in vitro and in vivo data presented here identify the critical roles of membrane protein CD83 in ovarian cancer cells." (PMID 32823589, 2020). "The results obtained show that ovarian cancer type II lysates induce differentiation of monocytes into macrophage-like cells with a CD1a+/HLA-DR+/CD83− phenotype and significantly higher CD86/HLA-DR expression." (PMID 28589429, 2017). "Furthermore, CD83 significantly promotes the spheroid formation of ovarian cancer cells in vitro and tumorigenic capacity of nude mice in vivo." (PMID 32823589, 2020). "Interestingly, CD83 was found to be hyperactivated in ovarian cancer spheroids derived from a single cancer cell." (PMID 32823589, 2020). "In this study, we found that CD83 associated with MAP3K7 and activated MAPK cascades to further regulate FOXO1/p21/CDK2/CCNB1 and STAT3/DKK1 signaling pathways, thus activating proliferation and spheroid formation of ovarian cancer cells." (PMID 32823589, 2020). "Hyperactivation of CD83 in ovarian cancer spheroids indicated that CD83 might be indispensable in the regulation of spheroid formation." (PMID 32823589, 2020). "Among ovarian cancer cell subpopulations, CD83 transcript was significantly upregulated (logFC >2, p < 0.01) in EpCAM+CD45+ highly aggressive, drug-resistant, and ovarian cancer stem cell-containing tumor cells compared to EpCAM+ cells, as revealed by GSE75036." (PMID 32823589, 2020). "However, the potential role of CD83 in ovarian cancer cell properties and development remains absolutely unknown." (PMID 32823589, 2020). "Collectively, our findings define a CD83-MAPK pathway in the regulation of proliferation and stemness in ovarian cancer cells, with potential therapeutic applications in blocking their progression." (PMID 32823589, 2020). "Taken together, these data suggested that CD83 formed a complex with TAK1-TAB1 on the cell membrane to further activate downstream p-ERK1/2-FOXO1-p21-CDK2 and STAT3-DKK1 signaling pathways in ovarian cancer cells." (PMID 32823589, 2020). "The activation of DCs (CD86 +, CD80+, CD83+, HLA-DR+), CTLs (CD3+CD8+) and NKT (CD3+CD56+) cells were all increased in 6B11-OCIK of the three patients during in vitro culture and showed good killing effect on ovarian cancer cells." (PMID 34408750, 2021). "We found that enforced CD83 expression in SKOV3, OVCAR3, and Caov3 cells significantly reduced their invasive capabilities to invade the matrigel-embedded transwell, whereas knockdown of CD83 stimulated the invasion of ovarian cancer cells." (PMID 32823589, 2020). "To obtain the expression information of CD83 in human ovarian cancer, we first re-analyzed gene expression microarray data of GSE105437 and found that CD83 level was higher (logFC > 2, p < 0.01) in high-grade serous ovarian cancers (HGSOC) (n = 10) than that in normal ovary tissues (n = 5)." (PMID 32823589, 2020). "We identify the activated TAK1-MEK1/2-ERK1/2 signaling, increased CDK2/cyclin B1 expression, and reduced FOXO1/p21 levels in CD83-overexpressed ovarian cancer cells, indicating that MAPK-ERK1/2-FOXO1 axis is involved in the activation of ovarian cancer cell proliferation by CD83." (PMID 32823589, 2020).
ovarian carcinoma (continued). "Moreover, CD83 functions through the activation of MAP3K7-MEK1/2-ERK1/2 cascades to further regulate downstream FOXO1/p21/CDK2/CCNB1 and STAT3/DKK1 signaling pathways, thus activating proliferation and spheroid formation of ovarian cancer cells, respectively." (PMID 32823589, 2020).